IL10 (interleukin 10)
Diseases named in the same sentence as IL10 in open-access papers (continued):
Sharing a sentence is not in itself a finding about the gene and the disease.
allergic asthma (continued). "However, our laboratory’s work using the same Foxp3creIL-4Rα−/lox mice in an allergic asthma model revealed that the profiles of CD4 T cells producing IL-17 and IL-10 in both the lymph nodes and lungs were similar." (PMID 39483462, 2024). "The key role played by IL-10 and TGF-β in the context of allergic asthma is now well established." (PMID 35757774, 2022). "In the model of allergic asthma, CD9+ B cells play a role in airway inflammation suppression by inhibiting Th2- and Th17-driven inflammation in an IL-10-dependent manner while MZB cells reduce the CD8 T cell function and IFN-γ+ CD4 T cells during the early stages of Leishmania donovani infection." (PMID 34594327, 2021). "We also verified the hypothesis that the tested therapeutic strategies could induce the production of IL-10 and TGF-β (i.e., crucial anti-inflammatory and immunosuppressive cytokines) by Treg cells and thereby counteract the development of allergic asthma." (PMID 34071080, 2021). "In allergic asthma, IL-10 level is elevated in serum, but decreases in bronchoalveolar lavage (BAL), which may reflect the binding of IL-10 to its receptors." (PMID 32024540, 2020). "IL-17 and IL-6 levels were significantly higher in plasma of children with allergic asthma than in those of the healthy control children (P < 0.01, P < 0.01), while TGF-β and IL-10 expression levels were markedly lower in the allergic asthma group than in the healthy control group (P < 0.01)." (PMID 32834826, 2020). "It was already described that IL-10 production by thymic Foxp3-negative Treg cells alleviates the lung eosinophil infiltration, globet cell hyperplasia and IgE and production in mice subjected to the OVA model of allergic asthma." (PMID 31805682, 2019). "In conclusion, EPA potentiated MSC-based therapy in experimental allergic asthma, leading to increased secretion of pro-resolution and anti-inflammatory mediators (RvD1, PGE2, IL-10, and TGF-β), modulation of macrophages toward an anti-inflammatory phenotype, and reduction in the remodeling process." (PMID 29881388, 2018). "IFN-γ and IL-10 levels did not increase after ovalbumin-induced allergic asthma in accordance with previous studies." (PMID 28646903, 2017). "In human allergic asthma, pulmonary Treg exhibited a significant decrease in suppressive activity and IL-10 production compared to healthy control and non-allergic asthmatic counterparts." (PMID 20230634, 2010). "This could be explained by the concomitant increase of IL-10 production by these cells, which has been shown to antagonize eosinophil recruitment but potentiate AHR in a similar mouse model of allergic asthma." (PMID 19811658, 2009). "In addition, EPA enhanced IL-10, TGF-β, RvD1, and PGE2 secretion by MSCs, which may induce anti-inflammatory and pro-resolution responses in allergic asthma." (PMID 29881388, 2018). "Moreover, the mean serum IL-10 levels were lower than the control group in newly diagnosed allergic asthma patients and non-treated severe persistent asthma patients." (PMID 23316107, 2012). "However, the basal serum cytokine profiles excluding the IL-10, patterns were not different between healthy and asthmatic individuals, regardless of whether the latter were newly diagnosed allergic asthma or non-treated severe persistent asthmatic patients." (PMID 23316107, 2012). "In an allergic asthma model, BPE-induced airway inflammation was demonstrated to be dependent on TLR4, influencing immune cell infiltration and the local production of IL-4 and IL-10 cytokines, without affecting airway hyperresponsiveness (AHR)." (PMID 35386993, 2021).
leukemia (73 papers, 2012 to 2025). A malignant (clonal) hematologic disorder, involving hematopoietic stem cells and characterized by the presence of primitive or atypical myeloid or lymphoid cells in the bone marrow and the blood. "Bioinformatics analyses revealed the involvement of miR-7974 in cellular pathways such as membrane dynamics and signal transduction (MAPK, NF-κB, and IL-10), and its association with Hodgkin’s lymphoma, leukemia, and nasopharyngeal neoplasms." (PMID 40431607, 2025). "When JAK2 mutations or aberrant STAT activation occur in leukemia cells, they often lead to the upregulation of pro-inflammatory cytokines such as IL-6, IL-10, TNF-α, and GM-CSF." (PMID 40486651, 2025). "IL-10’s impact extends beyond mere support for tumor cell survival; it has been implicated in promoting the stemness of leukemia stem cells via IL10/IL10R/PI3K/AKT signaling pathway, thereby potentially perpetuating disease relapse and resistance to therapy." (PMID 40681545, 2025). "T-cell populations from vehicle treated mice with leukemia exhibited significant upregulation of genes associated with immune exhaustion, such as Lag3, Tigit and Il10, as well as Ms4a2, an immune suppressive gene expressed by T-regulatory cells." (PMID 35831470, 2022). "RNA-sequencing of T-cells isolated from vehicle and rIL-12 treated mice with B-ALL revealed that the leukemia-induced increase in genes associated with exhaustion, including Lag3, Tigit, and Il10, was abrogated with rIL-12 treatment." (PMID 35831470, 2022). "Research results regarding the role of IL‐10 SNPs in the predisposition to leukemia are contradictory." (PMID 31373163, 2019). "For example, JAK2 mutations in leukemia cells can lead to the production of cytokines and growth factors such as IL-6, IL-10, and GM-CSF, which not only stimulate leukemia cell proliferation but also recruit immunosuppressive cells, like regulatory T-cells (Tregs), to the tumor microenvironment." (PMID 40486651, 2025). "In fact, low levels of IL-10 may pose a risk for transformation into leukemia." (PMID 38337668, 2024). "A study on B-ALL patients discovered that the expression levels of cytokines IL-7, IL-10 and IL-15 and their receptors were higher than those in healthy controls, suggesting the existence of a complex autocrine/paracrine mechanism underlying the regulation of leukemia cell functions." (PMID 28408741, 2017). "These Treg cells further sustain the stemness of leukemia stem cells (LSCs) through IL-10 secretion, driving disease progression and poor prognosis." (PMID 40557150, 2025). "Post allo-HSCT (allogeneic hematopoietic stem cell transplantation), CD4IL10 cells would inhibit graft vs host disease (GvHD) via secretion of IL-10, while boosting graft vs leukemia (GvL)." (PMID 38724673, 2024). "Overall, due to the complex crosstalk between the immune component of the tumor microenvironment and leukemia cells, the outcome of IL-10 pharmacological modulation is difficult to predict." (PMID 39598439, 2024). "Below, we show that BMSC donor variability can be monitored by IL-10 production of monocytes/macrophages using THP-1 cells (immortalized monocytic leukemia cells) co-cultured with BMSCs." (PMID 37686058, 2023). "IL-10 is a potent immunosuppressive cytokine, and IL-10-secreting B cells (B10 cells) have been identified as potent immunosuppressive agents that promote leukemia development." (PMID 37048814, 2023). "On the other hand, IL-10 concentration of leukemia patients was higher than those of head and neck carcinoma patients." (PMID 35476641, 2022). "We also used an independent sample T test to compare the cytokines interleukin 4 (IL-4) and interleukin 10 (IL-10) between different groups of these 50 leukemia patients, which were obtained by flow cytometry as stated in the previous complaint." (PMID 35721208, 2022). "So we used flow cytometry to detect IL-4 and IL-10 in 50 leukemia patients, and compared their differences between different groups." (PMID 35721208, 2022).
leukemia (continued). "It is clear that the combined increased gene expression of IL-1β, the secretion of IL-10, GM-CSF, and TNFα, and decreased secretion of IL-8 contribute to the anti-proliferative effects of carnosine on U937 promonocytic leukemia cells." (PMID 33809496, 2021). "IL-10 is a powerful immunosuppressor, and numerous reports have recognized IL-10-secreting B (B10) cells as potent immunosuppressive drivers accelerating the evolution of leukemia." (PMID 32102441, 2020). "What's more, the serum IL‐10 concentration was also increased in leukaemia mice and decreased when treated by VCR/BLZ945." (PMID 33037771, 2020). "Regulatory T-cells taken from children diagnosed with leukemia showed a higher suppressive capability, which was confirmed by detecting elevated levels of secreted IL-10 and TGF-beta." (PMID 30944830, 2019). "For example, in AML, leukaemia-derived M-CSF and IL-10 instruct stromal cells to secrete Gas6, which is the ligand for the TAM family tyrosine kinase receptor Axl." (PMID 25056697, 2014). "Prior to our work, supernatants of FD leukemia samples containing IL-6 and IL-10, TNF-α, and IL-1β were shown to trigger a block in DC differentiation in vitro." (PMID 23616009, 2013). "Correlating with the increased monocyte viability, the leukemia supernatant (1:3 dilution) induced the secretion of IL-10, TNF-α, IL-6, and IL-1β in both experiments." (PMID 23616009, 2013). "This study was the second in challenging the -1082 (IL10 gene) and -308 (TNF alpha gene) polymorphisms, together, in leukemia." (PMID 23213548, 2012). "The downregulation of the neutrophil degranulation pathway suggested an unfavorable environment for leukemia cell survival, while the concomitant upregulation of IL-10 signaling hinted at a complex interplay between proinflammatory, and cell survival pathways triggered by EF-24." (PMID 40986633, 2025). "Furthermore, the expression of most M2-associated genes, such as Arg1, CCL3, CCL17, CD206, IL-10, and TGF-β decreases with the infiltration of leukemia cells, whereas the expression of MMP9 and VEGFα increases in the advanced stages of leukemia." (PMID 38779660, 2024). "Additionally, neutrophils from the mice inoculated with TCL1 leukemia cells produced IL-10, IL-17, and IFN-γ at lower levels than neutrophils from the control mice, and adoptively transferred Treg did not reverse this outcome." (PMID 37817276, 2023). "Additionally, we show that Treg depletion and IL-10 neutralization induce changes in the leukemia microenvironment, partially restoring the “healthy” phenotype of neutrophils." (PMID 37817276, 2023). "The high levels of CD4+ T cells producing IL-10 were described in asymptomatic carriers as a possible immunoregulatory mechanism that guarantees their asymptomatic clinical status, and IL-10 blockage in ATLL patients collaborates with leukemia-initiating cell eradication." (PMID 37711742, 2023). "At the same time, AML cell lines were used as target cells to confirm the cytotoxic ability of IL-10 CAR-T which could effectively eliminate leukemia cells under the same condition as that of CD34+ UCB cells." (PMID 34392305, 2021). "Therefore, it indicated that leukemia cells were killed by IL-10 CAR-T cells before they were induced to proliferate." (PMID 34392305, 2021). "Indeed, inhibition of leukemia patients’ serum galectin-1 by OTX008 abrogates IL-10 production by dendritic and T cells, implying this molecule prevents immune deactivation." (PMID 34572756, 2021). "After 48 h of coculture, IL-10 CAR-T cells could effectively eliminate leukemia cells at an E:T ratio of 1:1, in some cases, even at an E:T ratio of 1:4." (PMID 34392305, 2021). "Finally, we found that exposure of human leukemia cells to PM III not only caused cytotoxicity, but also mediated an intrinsic immune reaction via enhanced Interferon, Il-2, Il-6, and Il-10 signaling." (PMID 30486233, 2018).
leukemia (continued). "Quantitative measurement of the serum cytokines in mice after the induction of leukemia (WEHI-3) revealed the IL-10 level at 156.30±4.10 pg/mL, whereas the levels of IFN-γ, TNF-α, IL-12β, and IL-2 were 52.63±5.03, 42.63±3.77, 185.40±15.24, and 14.81±0.74 pg/mL, respectively." (PMID 26752299, 2016). "Thus, combined treatment of leukemia cells with 9cRA and 1,25(OH)2D3 induces IL-10 protein secretion as well as increased expression of M2 macrophage markers." (PMID 25409436, 2014). "In fact, NK cell reactivity against 4-1BBL-positive leukemia cells could be restored by neutralization of IL-10 or TNF-α (with Infliximab)." (PMID 23316193, 2012). "Alloreactions mediated by donor NK cells can kill leukemia through graft-versus-leukemia (GvL) effect, promote engraftment through ablation of recipient T cells and protect against graft-versus-host disease (GvHD) through depleting recipient antigen-presenting cells and producing IL-10." (PMID 33287858, 2020). "BPA treatment in cell culture of a monocyte-like cell line derived from a leukemia patient and human peripheral blood macrophages have been found to release the proinflammatory cytokines TNFα and IL-6 and to decrease the anti-inflammatory/ regulatory cytokines IL-10 and TGFβ." (PMID 31551929, 2019). "In AML/ETO c-kitmut (A/Ec) leukemia mice, blocking the IL10/IL10R/PI3K/AKT signaling pathway extended their survival and significantly reduced the stemness of A/Ec leukemia cells." (PMID 40771826, 2025). "Immunosuppressive cytokines, such as IL-10 or TGF-beta, have been to date predominantly considered as unfavourable elements in leukaemia in the presence of their excess." (PMID 38275902, 2024). "Experiments with human monocytic leukemia cells (THP-1) revealed potential benefits of WPH on inflammation and endotoxin tolerance by modulating the immune response, and reducing IL-6 and IL-10 levels." (PMID 38594256, 2024). "CML red pulp macrophages (RPMs) are able to produce a variety of cytokines and chemokines such as IL-10, CCL3, CCL4, CCL5, CXCL1, TNF-α, and SCF, to sustain leukemia initial cells (LICs)." (PMID 38779660, 2024). "The Treg/Th17 and IL-10/IL-17 ratios were inversely correlated with CLL progression and were suggested as markers of leukemia outcomes." (PMID 37048814, 2023). "IL-10 (interleukin-10) and TNF-α as well as TGF-β (transforming growth factor β) and IFN-γ are assumed to have contrary effects in anti-leukemia immunity." (PMID 37610672, 2023). "IL-10 and TNF concentrations were significantly higher in the post-index group compared to the pre-index group among head and neck carcinoma and leukemia patients, respectively." (PMID 35476641, 2022). "Altogether, our data demonstrate that EOMES is indispensable for the development of IL-10-expressing, cytotoxic TR1 cells, which accumulate in LNs of CLL patients and control TCL1 leukemia in mice in an IL-10R-dependent manner." (PMID 33526861, 2021). "By exploiting the IL-10/JAK pathway, the human T-cell leukemia virus type 1 (HTLV-1) viral protein HBZ induced an increased IL-10 level, suppressed host immune response and therefore upgraded HTLV-1 proliferation in infected T leukemia cells." (PMID 34680295, 2021). "We further demonstrate the importance IL-10-mediated signaling in maintaining TR1 cells, which mediate effector activity and thus control of leukemia." (PMID 33526861, 2021). "An inverse correlation between Treg/Th17 and IL-10/IL-17 ratios and B-CLL progress was noticed, and this parameter was proposed as a marker of leukemia outcome." (PMID 32102441, 2020). "Second, leukemia cells remodel the microenvironment by releasing immunosuppressive factors (e.g., TGF-β, adenosine): the TGF-β induces the release of interleukin-10 (IL-10) after the expansion of regulatory T cells (Treg), and the TGF-β factor inhibits proliferation of effector T cells (Teff)." (PMID 41394969, 2025).
leukemia (continued). "IL-10's role as an anti-inflammatory cytokine involves inhibiting Th1 cytokines like IL-2 and IFN-γ, deactivating monocyte/macrophage proinflammatory cytokine synthesis, and playing a critical role in immune evasion in leukemia." (PMID 39118076, 2024). "Furthermore, there is evidence that Tregs directly regulate the stemness of AML cells through the release of IL-10 and a PI3K/AKT signaling pathway in preclinical leukemia models." (PMID 37205201, 2023). "Note that CLL cells in the blood were increased from baseline at these times, suggesting this latter observation was not simply due to fewer IL10-producing leukemia cells." (PMID 37114129, 2023). "With targeted RNA-sequencing, we found upregulation of immune exhaustion genes in T-cells, including Lag3, Tigit, and Il10, in mice with leukemia compared to those without." (PMID 35831470, 2022). "Tregs depletion at an advanced stage of leukemia progression increased the percentage of effector and IFN-γ-positive CD4+ and CD8+ T lymphocytes, significantly elevated IFN-γ concentration and reduced the concentration of IL-10 in the sera." (PMID 35296093, 2022). "In patients with leukemia, increased BAFF leads to increased IL-10+ B cells through TACI." (PMID 35250986, 2022). "This explains why, in the current study, recipients of a high-IL10-producing graft had a reduced incidence of aGVHD, but no concomitant increase in the incidence of relapse (i.e., dampened graft-versus-leukemia effect)." (PMID 36555525, 2022). "In the leukemia group, TNF concentration was higher in the post-index group, compared with those in the pre-index group (p < 0.05), and IL-10 concentration was significantly higher in the post-index group of the head and neck carcinoma group, compared to the pre-index group (p < 0.05)." (PMID 35476641, 2022). "Unfortunately, in these 50 patients with leukemia, there was no significant statistical difference in the expression of cytokines IL-4 and IL-10 between different groups." (PMID 35721208, 2022). "Since IL-10-driven signaling via p38 MAPK was shown to be important to maintain IL-10 production in TR1 cells, we investigated the role of IL-10R signaling in TR1 cells and the control of leukemia progression." (PMID 33526861, 2021). "To test whether IL-10 CAR-T cells could specifically recognize and kill primary AML cells, we further evaluated the cytotoxicity of IL-10 CAR-T cells against primary leukemia cells." (PMID 34392305, 2021). "Furthermore, we proposed to evaluate the patterns of dendritic cell lineages and of a subset of immunomodulatory cytokines (IL-10, TNF-α, IL-6, and IL-1β) during the course of ITD+ leukemia." (PMID 23616009, 2013). "As for GZMB+ Bregs, we found that BANK1 was decreased in other subtypes of Bregs, including IL10+ and CD24hiCD38hi transitional regulatory B cells, along with BANK1 was down-regulated in activated/differentiated B cells, as in CD40-activated B cells, in leukemia and plasma cells." (PMID 33815360, 2021). "In addition, even though the incorporation of IL-10 in the CAR cassette led to phenotypes change, it had few adverse effects on the survival and biological activity of IL-10 CAR-T cells and did not cause excessive proliferation of leukemia cells." (PMID 34392305, 2021). "In that regard, we evaluated if cytokines (IL-10, TNF-α, IL-6, and IL-1β) proposed by several groups as indicators of a broad range of immunopathological conditions affecting cancer could also serve as potential biomarkers to predict ITD+ leukemia relapse." (PMID 23616009, 2013). "GITRL signaling into various leukemia cells induced the production of TNF-α, IL-6, and IL-8, or IL-10 that not only enhanced proliferation and survival of leukemia cells but also could suppress the immune system." (PMID 23316193, 2012).